SNORD95 (small nucleolar RNA, C/D box 95)
Synonyms: U95
Gene: Small nucleolar RNA gene on chromosome 5 (181,243,312 to 181,243,379, reverse strand). Ensembl gene ENSG00000264549.
Gene Ontology:
Biological process: RNA processing
Cellular component: nucleolus
Homologues: Orthologues: chimpanzee SNORD95 (100% identical), macaque SNORD95 (99% identical), rabbit SNORD95 (93% identical), pig SNORD95 (91% identical), mouse Gm25296 (90% identical), rat LOC120095394 (90% identical), guinea pig SNORD95 (88% identical), mouse Snord95 (85% identical), rat Snord95 (85% identical).
Diseases named in the same sentence as SNORD95 in open-access papers:
SNORD95 is named in the same sentence as 1 disease in open-access papers, as found by Europe PMC text mining. Sharing a sentence is not in itself a finding about the gene and the disease.
SNORD95 shares sentences with these, for which no sentence is quoted: lung disease (1 paper).